NPC1L1 (NPC1 like intracellular cholesterol transporter 1)
Diseases named in the same sentence as NPC1L1 in open-access papers (continued):
Sharing a sentence is not in itself a finding about the gene and the disease.
breast carcinoma (7 papers, 2013 to 2025). "It is worth noting that the genetic proxy inhibition of NPC1L1 is significantly associated with a reduced risk of breast cancer." (PMID 40430847, 2025). "Genetically proxied inhibition of HMG-CoA reductase and NPC1L1 was significantly associated with lower odds of breast cancer, while genetically proxied inhibition of PCSK9 was associated with reduced risk of prostate cancer." (PMID 35151363, 2022). "The results of leave-one-out sensitivity analyses showed that no individual SNP substantially drove the associations of HMG-CoA reductase and NPC1L1 with breast cancer." (PMID 35151363, 2022). "Genetically proxied inhibition of HMG-CoA reductase and NPC1L1 was significantly associated with lower odds of breast cancer (especially ER-positive breast cancer), while genetically proxied inhibition of PCSK9 was associated with reduced risk of prostate cancer." (PMID 35151363, 2022). "In the present study, we first found that genetically proxied inhibition of HMG-CoA reductase and NPC1L1 were significantly associated with lower odds of breast cancer (especially ER-positive breast cancer), while the inhibition of PCSK9 was associated with reduced risk of prostate cancer." (PMID 35151363, 2022). "Estimates for NPC1L1 were suggestive of risk-increasing effects of raised LDL-cholesterol on breast cancer and ER-positive breast cancer risk in inverse variance-weighted analysis, but MR Egger estimates were in the opposite direction, casting doubt on the validity of MR assumptions in this case." (PMID 30262900, 2018). "Our tests have confirmed that Ezetimibe, an NPC1L1 inhibitor, exhibits significant inhibitory activity against various breast cancer cell lines." (PMID 40430847, 2025). "Currently, research on NPC1L1’s role in breast cancer is sparse, and the precise mechanism by which PARP inhibitors regulate NPC1L1 in TNBC remains uncharted." (PMID 40430847, 2025). "Preclinical and epidemiological studies have also suggested a significant correlation between inhibiting NPC1L1 and a reduction in breast cancer incidence." (PMID 40430847, 2025). "We explored the influence of PARP inhibitor-induced upregulation of NPC1L1 on the behavior of CD8+ T cells in breast cancer." (PMID 40430847, 2025). "Genetically proxied inhibition of HMG-CoA reductase (OR: 0.84; 95% CI 0.74–0.95; P = 0.005) and NPC1L1 (OR: 0.72; 95% CI 0.58–0.90; P = 0.005) equivalent to a 1-mmol/L (38.7 mg/dL) reduction in LDL-C was associated with reduced breast cancer risk." (PMID 35151363, 2022). "This suggests that NPC1L1 inhibition might hold clinical promise in augmenting the activity of CD8+ T cells infiltrating breast cancer." (PMID 40430847, 2025). "Genetically proxied inhibition of HMG-CoA reductase (OR: 0.84; 95% CI 0.74–0.95; P = 0.005) and NPC1L1 (OR: 0.72; 95% CI 0.58–0.90; P = 0.005) equivalent to a 1-mmol/L (38.7 mg/dL) reduction in LDL-C was significantly associated with a reduced risk of breast cancer, respectively." (PMID 35151363, 2022). "We found that genetically proxied inhibition of HMG-CoA reductase and NPC1L1 but not PCSK9 were significantly associated with reduced risk of breast cancer (mainly ER-positive breast cancer), while only genetically determined PCSK9 inhibition was associated with low odds of prostate cancer." (PMID 35151363, 2022). "Leveraging diverse algorithms from the Tumor Immune Estimation Resource (TIMER) database, we discovered an inverse relationship between NPC1L1 expression levels and the infiltration of CD8+ T cells in breast cancer tissues." (PMID 40430847, 2025). "Herein, we conducted a two-sample MR study to assess the causal associations of several LDL-C-lowering drug targets (HMG-CoA reductase, NPC1L1, and PCSK9) with breast cancer and prostate cancer." (PMID 35151363, 2022).
breast carcinoma (continued). "Recently, genetically proxied inhibition of HMG-CoA reductase but not NPC1L1 and PCSK9 was associated with lower odds of epithelial ovarian cancer in MR study, while no such MR study was currently available for breast cancer and prostate cancer." (PMID 35151363, 2022).
pancreatic cancer (7 papers, 2021 to 2025). "In 2017, through a multi‐omics analysis of 29 PDAC xenografts, the authors found that NPC1L1 inhibitors, such as Ezetimibe, are effective therapies for pancreatic cancer." (PMID 40145543, 2025). "These lend credence to the idea that NPC1L1 might work well as a therapeutic target for pancreatic cancer." (PMID 36034854, 2022). "We established and validated a prognostic model for pancreatic cancer with 7 signatures, including ADH1C, APOE, RAP1GAP, NPC1L1, P4HB, SOD2, and TNFSF10." (PMID 38685045, 2024). "Additionally, NPC1L1 may be a valuable therapeutic target for pancreatic cancer." (PMID 36034854, 2022).
colorectal cancer (5 papers, 2015 to 2025). A primary or metastatic malignant neoplasm that affects the colon or rectum. "Colorectal cancer is strongly associated with lipid metabolism; NPC1L1 is a sterol transporter that is a key regulator of lipid homeostasis." (PMID 34503106, 2021). "Since NPC1L1 genotype is different amongst people, our results may also contribute to explain differences in colorectal cancer susceptibility amongst people." (PMID 25881076, 2015). "The most recent research indicates that NPC1L1 can be employed as a standalone prognostic marker in colorectal cancer." (PMID 36034854, 2022). "It was revealed that NPC1L1 has value as a standalone prognostic factor for colorectal cancer, and it was found that the NPC1L1 expression was highly correlated with the prognosis of the disease." (PMID 36034854, 2022). "NPC1L1, along with other known prognostic markers, can be independent prognostic markers for colorectal cancer." (PMID 36034854, 2022). "Additionally, the inflammatory markers pc-Jun, p-ERK, and caspase-1 p20 in colorectal cancers were considerably decreased by NPC1L1 knockdown." (PMID 36034854, 2022). "NPC1L1 has an impact on colorectal cancer patients’ overall survival, with patients in the NPC1L1 high-expression group having a worse OS than NPC1L1 patients, according to a KM analysis of the NPC1L1 low-expression group and the NPC1L1 high-expression group on OS." (PMID 36034854, 2022).
steatosis (5 papers, 2019 to 2024). Increased lipid within the cytoplasm of cells. "Our results revealed that hepatic NPC1L1 is a novel NAFLD risk factor contributing to steatosis formation that is rescued by ezetimibe; additionally, our findings uncover feasible opportunities for repositioning drugs to treat NAFLD in the near future." (PMID 32123832, 2019). "The detailed molecular basis underlying the early stage of hepatic NPC1L1‐mediated steatosis is an important research topic for future studies." (PMID 32123832, 2019). "We therefore concluded that hepatic NPC1L1 is a novel exacerbating factor of steatosis amendable to therapeutic intervention." (PMID 32123832, 2019). "In this study, we investigated the biochemical features of hepatic NPC1L1-mediated steatosis to aid further understanding of NAFLD development in L1-Tg mice." (PMID 31883528, 2019). "We therefore realize that the phenotypic expression of hepatic NPC1L1-mediated steatosis must depend on diet, especially in terms of the quantity and quality of NPC1L1 substrates, such as cholesterol." (PMID 31883528, 2019). "Unlike the livers of wild-type mice that have little expression of hepatic Npc1l1, the livers of L1-Tg mice displayed time-dependent changes that indicated steatosis formation." (PMID 31883528, 2019). "Hepatic NPC1L1 exacerbates diet-induced steatosis, which was accompanied by decreased hepatic ability of VLDL-TG secretion." (PMID 31883528, 2019). "This interpretation agreed with the model that hepatic NPC1L1 should be a cholesterol re-absorber from bile and the prevention of hepatic NPC1L1-mediated steatosis formation by the administration of ezetimibe, an NPC1L1 inhibitor." (PMID 31883528, 2019). "Based on the presence of weak liver injury as well as the elevation of oxidative and ER stress in the livers of L1-Tg mice fed a HFD, NPC1L1-mediated lipid overload should induce several types of hepatic stresses, resulting in steatosis formation." (PMID 31883528, 2019). "To further examine the involvement of hepatic NPC1L1 in steatosis formation, we next administered the NPC1L1‐selective inhibitor ezetimibe to L1‐Tg mice for 2 weeks by mixing it in the mouse feed." (PMID 32123832, 2019). "In conclusion, we demonstrated that hepatic NPC1L1 can exacerbate steatosis with possibility that biliary‐derived cholesterol is involved in NAFLD progression." (PMID 32123832, 2019). "Results in this study uncovered three features of the early stage of hepatic NPC1L1-mediated steatosis." (PMID 31883528, 2019). "In this context, dietary components absorbed by intestinal NPC1L1 is also likely to contribute to steatosis formation, because the L1-Tg mice have both hepatic and intestinal expression of NPC1L1, similar to humans." (PMID 31883528, 2019). "To examine the effect of Tlr4 inhibition on hepatic NPC1L1‐mediated steatosis, we fed L1‐Tg mice a HFD containing IAXO101 (12 μg/g of feed), a commercially available synthetic antagonist of TLR4 signaling, for 2 weeks." (PMID 32123832, 2019). "The present study successfully provided further details regarding the contribution of hepatic NPC1L1 to the exacerbation of steatosis." (PMID 31883528, 2019). "Indeed, overexpression of hepatic NPC1L1 in the liver leads to free cholesterol accumulation and exacerbation of steatosis." (PMID 38953111, 2024). "At univariate analyses, NPC1L1 mRNA expression was significantly lower in liver grafts with predominant Ld-MaS compared to both those with predominant Sd-MaS (p = 0.011) and those with nil-Steatosis (p = 0.003)." (PMID 34198853, 2021). "LCN2 is a reliable indicator of hepatic damage and positively correlated with inflammation; therefore, the elevation of Lcn2 in the livers of L1-Tg mice fed a HFD supports a previous study that shows that the activation of innate immune systems is related to hepatic NPC1L1-mediated steatosis." (PMID 31883528, 2019).
steatosis (continued). "Indeed, transgenic mice with hepatic expression of human NPC1L1 under a liver-specific promoter (L1-Tg mice) developed steatosis with a high-fat diet (HFD) containing cholesterol within a few weeks." (PMID 31883528, 2019). "This trend might imply that hepatic NPC1L1‐dependent re‐uptake of cholesterol followed by the activation of TLR4‐mediated cellular responses may be involved in steatosis formation." (PMID 32123832, 2019). "Considering that the expression levels of hepatic NPC1L1 in L1-Tg mice are relatively similar to that of humans, L1-Tg mice with diet-induced steatosis are expected to be a useful model for investigating the developmental mechanisms of NAFLD and exploring new therapeutic targets." (PMID 31883528, 2019). "Moreover, hepatic NPC1L1‐mediated steatosis was not only prevented, but completely rescued, by orally administered ezetimibe, a well‐used lipid‐lowering drug on the global market, even under high‐fat diet feedings." (PMID 32123832, 2019). "Indeed, the hepatic NPC1L1-mediated steatosis was prevented by the administration of a toll like receptor 4 (TLR4) inhibitor and attenuated by macrophage depletion." (PMID 31883528, 2019). "An important question for future studies is to determine whether TLR4 is a dependent or independent factor in the development of hepatic NPC1L1‐mediated steatosis." (PMID 32123832, 2019). "Furthermore, administration of a TLR4 inhibitor also prevented the hepatic NPC1L1‐mediated steatosis formation, suggesting a latent link between physiological roles of hepatic NPC1L1 and regulation of innate immune system." (PMID 32123832, 2019). "Here, we experimentally demonstrate that hepatic Niemann‐Pick C1‐Like 1 (NPC1L1), a cholesterol re‐absorber from bile to the liver, can cause steatosis, an early stage of NAFLD using genetically engineered L1‐Tg mice characterized by hepatic expression of NPC1L1 under the control of ApoE promoter." (PMID 32123832, 2019). "In this study, we identified hepatic NPC1L1 as a novel factor that exacerbates steatosis." (PMID 32123832, 2019). "Second, proinflammatory processes could be involved in hepatic NPC1L1-mediated steatosis." (PMID 31883528, 2019). "Considering the physiological role of hepatic NPC1L1 as a cholesterol re‐absorber from bile, the NPC1L1‐mediated increase of hepatic cholesterol seems to be followed by TG accumulation in the liver, resulting in the steatosis formation, which was only observed in L1‐Tg mice." (PMID 32123832, 2019). "Indeed, ezetimibe administration could not only prevent but could also cure hepatic NPC1L1‐mediated steatosis." (PMID 32123832, 2019). "Moreover, we found that a decrease in VLDL-TG-secretion ability could be involved in hepatic NPC1L1-mediated steatosis." (PMID 31883528, 2019). "Moreover, to exclude the possibility that unexpected genetic alterations in L1‐Tg mice may have affect steatosis formation, we transiently expressed NPC1L1 in the liver of WT mice using an NPC1L1‐expressing adenovirus (L1‐Av)." (PMID 32123832, 2019). "As demonstrated, steatosis was induced in mice fed a HFD when the liver expressed NPC1L1 in this study, indicating that this phenotype is governed by hepatic NPC1L1 substantially." (PMID 31883528, 2019). "Our findings strongly suggest that hepatic NPC1L1 can exacerbate NAFLD, including steatosis in humans." (PMID 32123832, 2019). "A recent meta-analysis showed that administration of ezetimibe, an NPC1L1 inhibitor, improves liver inflammatory activity but not steatosis in patients with NASH." (PMID 34198853, 2021). "Re‐analysis of this data set showed that NPC1L1‐expression levels in the livers of patients with steatosis and NASH were higher than those in normal controls, suggesting that subjects with higher levels of NPC1L1 may be more prone to NAFLD." (PMID 32123832, 2019).
steatosis (continued). "In this context, it is important to examine whether hepatic NPC1L1 can exacerbate steatosis (an initial feature of NAFLD), and whether ezetimibe can attenuate NPC1L1‐dependent hepatic disorder." (PMID 32123832, 2019). "This last finding could be due to the fact that livers with predominant Ld-MaS, which in our study are the majority, have a very low expression of NPC1L1, lower than both that of livers with predominant Sd-MaS and that of livers without steatosis." (PMID 34198853, 2021). "Considering the not-so-limited substrate specificity of NPC1L1, some cholesterol derivatives, such as oxidized-cholesterols, might also be involved in the NPC1L1-mediated exacerbation of steatosis." (PMID 31883528, 2019). "Moreover, although the molecular basis remains to be elucidated, simultaneous inhibition of hepatic NPC1L1 and TLR4 might have greater therapeutic effect in treating steatosis versus monotherapy with either inhibitor." (PMID 32123832, 2019). "Thus, the current experimental design could not clarify the potential contribution of intestinal Npc1l1 to the steatosis formation in L1-Tg mice, which should be assessed in future studies using an intestinal Npc1l1 specific loss-of-function model." (PMID 31883528, 2019).
colitis (4 papers, 2015 to 2024). Inflammation of the colon. "Wild-type mice and NPC1L1−/− (NPC1L1 knockout) mice were treated with azoxymethane (AOM)-dextran sodium sulfate (DSS) to induce colitis-associated colorectal tumorigenesis." (PMID 25881076, 2015). "Based on these results, NPC1L1 knockout reducing colitis-associated tumorigenesis is unlikely due to NPC1L1 ablation in colorectal mucous membranes." (PMID 25881076, 2015). "Our results provide the first evidence that NPC1L1 knockout protects against colitis-associated tumorigenesis." (PMID 25881076, 2015). "Interestingly, NPC1L1 knockout mice showed protective effects against colitis-associated tumorigenesis by decreasing plasma lipids, especially cholesterol, to reduce inflammation and β-catenin, p-c-Jun, and p-ERK signaling." (PMID 38672177, 2024). "Their findings have shown that NPC1L1 deletion in mice reduced carcinogenesis linked to colitis." (PMID 36034854, 2022). "Therefore, it is unlikely that the NPC1L1 knockdown inhibits the growth of malignancies linked to colitis." (PMID 36034854, 2022). "It is logical to consider that β-catenin, p-c-Jun and p-ERK may be involved in the mechanism of NPC1L1 knockout protecting mice from colitis-associated tumorigenesis." (PMID 25881076, 2015). "NPC1L1 knockout in mice protects mice against colitis-associate colorectal tumorigenesis." (PMID 25881076, 2015). "Here, we testified that NPC1L1−/− mice were resistant to colitis-associated tumorigenesis." (PMID 25881076, 2015). "Our results testify that NPC1L1 knockout in mice protects against colitis-associated tumorigenesis." (PMID 25881076, 2015). "Therefore, NPC1L1 knockdown decreases carcinogenesis associated with colitis, which may be brought on by the decrease in plasma lipids, particularly cholesterol, brought on by its knockdown, which lessens the sensitivity to inflammatory stimuli." (PMID 36034854, 2022). "Hence, plasma lipid, especially cholesterol, may be involved in the mechanism of NPC1L1 knockout reducing colitis-associated tumorigenesis." (PMID 25881076, 2015).
colon cancer (4 papers, 2022 to 2025). "For example, in colon cancer, NPC1L1 expression is significantly associated with advanced stages, particularly in patients with lymph node involvement and higher AJCC stage, suggesting its role in cancer progression." (PMID 39598242, 2024). "Decreased expression of NPC1L1 in subcutaneous adipose tissue was associated with a reduced risk of anal canal cancer (OR = 0.44, 95% CI: 0.21–0.94, p = 0.04), but an increased risk of colon cancer (OR = 1.26, 95% CI: 1.01–1.57, p = 0.04)." (PMID 40443776, 2025). "Taken together, these findings suggest that the function of NPC1L1 is cancer type-specific, assuming different roles in various cancers such as RCC, colon cancer, and HCC." (PMID 39598242, 2024).
Insulin resistance (4 papers, 2019 to 2025). Increased resistance towards insulin, that is, diminished effectiveness of insulin in reducing blood glucose levels. "In contrast, an animal study showed that NPC1L1 inhibitors reduced diet-induced hyperglycemia and insulin resistance." (PMID 40225015, 2025). "Further, insulin resistance enhances intestinal cholesterol absorption, attributable to changes in Niemann–Pick C1-Like 1 (NPC1L1)." (PMID 35408799, 2022). "Insulin resistance enhances intestinal cholesterol absorption attributable to changes in NPC1L1." (PMID 35408799, 2022). "MR validated the presence of multiple causative risk factors, particularly APOC3, IL-1, IL6, insulin resistance, height, non-fasting glucose, telomere length, HMGCR, and Niemann-Pick C1-Like 1 (NPC1L1)." (PMID 38601677, 2024).
Stroke (4 papers, 2019 to 2024). Sudden impairment of blood flow to a part of the brain due to occlusion or rupture of an artery to the brain. "The genetic variants at or near HMGCR, NPC1L1, and APOC3 were predicted to decrease lacunar stroke incidence in drug-target MR analysis." (PMID 38275377, 2023). "The SMR method was conducted to assess the association between the expression of HMGCR, PCSK9, NPC1L1, and APOB and stroke outcome." (PMID 37528862, 2023). "SMR association between expression of gene HMGCR, PCSK9, NPC1L1 or APOB and stroke and its subtypes." (PMID 37528862, 2023). "Firstly, the lack of available eQTLs in blood for NPC1L1 and APOB limited our ability to explore the association between NPC1L1 and APOB expression in blood and stroke." (PMID 37528862, 2023). "IVW-MR association between LDL cholesterol mediated by gene HMGCR, PCSK9, NPC1L1, or APOB and stroke and its subtypes." (PMID 37528862, 2023).